HIF1A (hypoxia inducible factor 1 subunit alpha)
Diseases named in the same sentence as HIF1A in open-access papers (continued):
Sharing a sentence is not in itself a finding about the gene and the disease.
clear cell renal cell carcinoma (continued). "HIF1α has been termed a tumor-suppressor in clear cell renal cell carcinoma (ccRCC), primarily based on functional proliferation studies in cell lines (in vitro and in vivo) with genetic manipulation, and the adverse prognosis of 14q-deleted ccRCC patients." (PMID 33077781, 2020). "Clear cell Renal Cell Carcinoma (ccRCC) is the only malignancy in which HIF1α has been stated to have a tumor-suppressive role." (PMID 33077781, 2020). "Intriguingly, Gal-1 has been reported to be the downstream effector of HIF1α in clear cell renal cell carcinoma." (PMID 31640796, 2019). "Given that mitochondrial O2•− has been implicated in the activation of HIF-1α, decreased SOD2 expression by HIF-1α was proposed as a positive feedback mechanism for HIF-1α signaling in renal clear cell carcinoma." (PMID 29099803, 2017). "A similar situation is seen in clear cell renal carcinoma, where the negative regulator of HIF1α and HIF2α is frequently lost, and HIF2α is an oncoprotein and HIF1α acts as a tumor suppressor." (PMID 26849233, 2016). "Hypoxia inducible factor 1 alpha (HIF1α) is a transcription factor that is frequently stabilized and active in human clear cell renal cell carcinoma (ccRCC)." (PMID 25830305, 2015). "Hypoxia Inducible Factors (HIF1α and HIF2α) are commonly stabilized and play key roles related to cell growth and metabolic programming in clear cell renal cell carcinoma." (PMID 24879016, 2014). "For example, VHL dependent E-cadherin regulation by HIF-1α is carried out via this indirect form of regulation in clear cell renal carcinoma cells (CC-RCC)." (PMID 23469202, 2013). "We first evaluated the protein expression of HIF1α and HIF2α in 15 different clear cell renal carcinoma cell lines established from patient tumors in our laboratory." (PMID 23178531, 2012). "Strong up-regulation of nuclear HIF-1α in peritumoral and intratumoral macrophages was observed in the positive control case of renal clear cell carcinoma." (PMID 20716170, 2010). "Previously, GAL3ST1 was identified as a HIF1α target gene in renal clear cell carcinoma." (PMID 39000386, 2024). "To further validate these findings, we examined the effect of USP43 loss in clear cell renal carcinoma cell (ccRCC) lines that have constitutive activation of both HIF-1 and HIF-2 (RCC4 cells, HIF-1α+, HIF-2α+ and VHL−), or only encode HIF-2α (786-0 cells, HIF-1α−, HIF-2α+ and VHL−)." (PMID 39009674, 2024). "Results from Cox regression analysis of factors important for cancer-specific survival in 149 patients with clear cell renal cell carcinoma, adjusted for age, gender, tumor size (mm), tumor grade, tumor stage, and HIF-1α, HIF-2α, and HIF-3α nuclear and cytoplasmic expression levels, respectively." (PMID 38571885, 2024). "In clear cell renal cell carcinoma (ccRCC), however, the role of HIF1α has been debated." (PMID 33077781, 2020). "In the following, we verify whether TR-metabolite associations inferred in vitro are relevant also in an in vivo context, by testing the well-known role of HIF-1A as a key oncodriver in clear-cell renal cell carcinoma." (PMID 31015463, 2019). "Vhl-deficient renal clear cell carcinoma cells, ROC-4, where HIF-1α protein is known to accumulate irrespective of oxygen conditions was used as a positive control for IHC and, as anticipated, we detected nuclear HIF-1α." (PMID 31821370, 2019). "The tumor-suppressing activity of HIF-1α is strongly indicated by the genetic evidence that focal, homozygous deletions of HIF1A gene are found in many VHL-deficient renal clear-cell carcinoma cell lines and the functional evidence that HIF-1α inhibits cell proliferation and tumor growth." (PMID 25893706, 2015). "The lncRNA hypoxia inducible factor 1 alpha-antisense RNA 2 (HIF1A-AS2) was first discovered in 1999 by Thrash-Bingham and Tartof, who identified a transcript that could bind complementarily with the 3’-untranslated region (UTR) of HIF1α mRNA in renal clear cell carcinoma." (PMID 40098697, 2025).
clear cell renal cell carcinoma (continued). "Interestingly, HIF-1α also has dual roles in cancer, being important for tumourigenesis in cancer such as colon and breast, but acting more as a tumour suppressor in cancers such as renal clear cell cancer." (PMID 28304334, 2017). "Biallelic mutation of the VHL ubiquitin ligase leads to constitutive activation of hypoxia inducible factors HIF1A and HIF2A and is generally a truncal event in clear cell renal carcinoma." (PMID 41102155, 2025). "In clear cell renal cell carcinoma, 80% of cases have biallelic inactivation of the VHL gene, leading to constitutive activation of both HIF1α and HIF2α." (PMID 34353313, 2021). "The selenium-containing protein Se-methylselenocysteine can inhibit HIF-1α, HIF-2α, and VEGF in clear cell renal carcinoma." (PMID 32872195, 2020). "Interestingly, stabilization of hypoxia-inducible factor 1 alpha (HIF1α) was associated with downregulation of PGC1α TFAM mRNA and protein levels in likewise chemoresistant Von Hippel-Lindau tumor suppressor protein (VHL)-deficient clear-cell renal carcinoma tumors and cell lines." (PMID 29361779, 2018). "In clear cell renal cell carcinoma (CCRCC) VHL-defective RCC4 and RCC10 cells, binding of HIF-1α/2α to the reverse HRE (rHRE) on the HIF1A promoter, leads to H3K9 methylation, H3K4 de-methylation and HIF1A repression." (PMID 26647819, 2015). "Interestingly, in clear renal cell carcinoma, PGC-1α is suppressed by an HIF-1α/Dec1-dependent mechanism." (PMID 40713487, 2025). "Hypoxia inducible factors, HIF‐1α and HIF‐2α, and their main regulators, the prolyl hydroxylase domain proteins (PHDs), mediate cellular response to hypoxia and contribute to tumor progression in clear cell renal cell carcinoma (ccRCC)." (PMID 38400673, 2024). "Clear cell renal cell carcinoma (ccRCC), the most common form of kidney cancer, is typically initiated by inactivation of the von Hippel Lindau (VHL) gene, which results in the constitutive activation of the hypoxia inducible factors, HIF-1α and HIF-2α." (PMID 36097192, 2022). "It has been reported that decreased TCEB1 expression or function can suppress the ubiquitination of HIF-1α, enhancing its expression, and mediating the tumorigenesis of clear-cell renal cell carcinoma; however, this is not well-understood." (PMID 34163032, 2021). "In clear cell renal cell carcinoma, VHL loss-of-function mutations frequently leads to VHL deficiency and hence the upregulation of HIF-1α protein expression regardless of oxygen concentration." (PMID 34611473, 2021). "Taken together, the data indicate that HIF1α is not a target of 14q deletion in clear cell renal cancer and that it is not a tumor-suppressor in this malignancy." (PMID 33077781, 2020). "New treatment modalities targeted to HIF-1α and HIF-2α might be planned as well as VEGF-targeted therapies in the management of clear cell renal cell carcinomas." (PMID 27583351, 2017). "However, in clear cell renal cell carcinoma, preliminary data suggest that SIRT4 interacts directly with HIF1A and may reduce HIF1A protein levels." (PMID 38276269, 2023).
pulmonary fibrosis (87 papers, 2009 to 2026). Chronic progressive interstitial lung disorder characterized by the replacement of the lung tissue by connective tissue, leading to progressive dyspnea, respiratory failure, or right heart failure. "One of the many key causes of genetic changes in the disease is high levels of HIF-1α, and researchers have found that patients with idiopathic pulmonary fibrosis have abnormally elevated levels of lactic acid in the lungs and serum." (PMID 40710342, 2025). "Administering pharmacological concentrations of AsA (an alternative to HIF-1 inhibitors) inhibited the progression of both cancer and underlying pulmonary fibrosis, with effects comparable to those seen with HIF-1α inhibitors." (PMID 38012636, 2023). "HIF-1α is, in turn, a key mediator of hypoxia-associated fibroblast proliferation in the context of pulmonary fibrosis." (PMID 34349652, 2021). "Researchers have recently used normal human bronchial epithelial cells in vitro to confirm that HIF-1a is associated with pulmonary fibrosis after transplantation." (PMID 30696477, 2019). "Finally, we investigated whether targeting HIF‐1α and its associated metabolic changes could be a potential treatment for pulmonary fibrosis." (PMID 39721015, 2025). "Taken together, these findings suggest that in PS-NPs-induced pulmonary fibrosis, potent positive transcription factors such as HIF-1α and NRF2 are strongly activated and exert a sustained upward drive on FTL expression." (PMID 41560817, 2026). "Consistent with this, HIF1A is typically elevated in experimental models of pulmonary fibrosis, and our data similarly show increased HIF1A protein in PS-NPs–exposed lungs." (PMID 41560817, 2026). "CCT6A is a member of the chaperone-containing TCP1 complex (CCT), which reduces lung fibrosis by inhibiting HIF-1α protein levels and lowering lactate." (PMID 40710342, 2025). "Expanding on existing studies, this investigation provides a more in‐depth analysis of how HIF‐1α impacts ECM remodeling in pulmonary fibrosis, highlighting its potential as a therapeutic target." (PMID 39721015, 2025). "The AKT pathway is involved in pulmonary fibrosis by regulating its downstream, such as mTOR, HIF-1α, and the FOX family." (PMID 40743122, 2025). "Our findings support the significance of HIF‐1α as a molecular target for the reversal of pulmonary fibrosis and provide valuable information for the development of innovative therapeutic strategies." (PMID 39721015, 2025). "Here, we examined the role of HIF-1α in TGF-β1-induced fibrosis using cell lines relevant to lung fibrosis, including alveolar basal epithelial cells (A549), human lung fibroblasts (MRC-5), and bronchial epithelial cells (BBM)." (PMID 41344160, 2025). "This study identifies oxidative stress as a critical driver of HIF-1α hyperstabilization in pulmonary fibrosis, establishing a mechanistic link between TGF-β1 signaling, NOX-derived ROS, and the functional impairment of PHD2." (PMID 41344160, 2025). "Multiple studies have reported localized hypoxia and subsequent elevation of HIF-1α levels in the lungs of patients with pulmonary fibrosis." (PMID 41344160, 2025). "Further testing in mice with silica dust‐induced lung fibrosis confirmed the previous findings, as there was a significant increase in HIF‐1α expression observed in silicosis nodules." (PMID 39721015, 2025). "Inhibition of DRP1 has been shown to block mitochondrial fission in fibroblasts via ROS/HIF‐1α, and thereby mitigate the progression of pulmonary fibrosis." (PMID 40709564, 2025). "It suppresses HIF-1α-mediated lactate production by promoting VHL-dependent ubiquitination and degradation of HIF-1α, thereby inhibiting lipid accumulation and alleviating bleomycin-induced pulmonary fibrosis in mice." (PMID 40791591, 2025). "Hypoxia and hypoxia-inducible factor 1 alpha (HIF-1α) play a central role in the pathogenesis of pulmonary fibrosis." (PMID 41155396, 2025).
pulmonary fibrosis (continued). "Our study showed that HIF‐1α plays a crucial role in modulating metabolic alterations in silica dust‐induced pulmonary fibrosis." (PMID 39721015, 2025). "The HIF‐1α inhibitor LW6 effectively ameliorated silica dust‐induced pulmonary fibrosis in mice, either by interfering with silicosis progression or by promoting regression of established fibrosis." (PMID 39721015, 2025). "Piezo1 is activated in response to cyclic pressure and drives c-JUN activation, endothelin-1 overexpression and HIF1α stabilization, facilitating the pro-inflammatory program in mouse lung fibrosis." (PMID 38267432, 2024). "Given our findings, the Hif-1α-EGFR signaling pathway appears to be crucial for APD's regulation of ferroptosis in pulmonary fibrosis." (PMID 38584671, 2024). "Inhibition of the TGF‐β/HIF‐1α/PDK1 axis via deletion of HIF‐1α expression or targeting PDK1 by drug‐reduced pulmonary fibrosis." (PMID 39417702, 2024). "Activated pathways in BAC/APOL1-G1 placenta include inflammatory and autoimmune disease related pathways such as pathogen induced cytokine storm pathway, pulmonary fibrosis idiopathic signaling pathway, and HIF1α pathway." (PMID 39803524, 2024). "Further investigation into the relationship between HIF-1α and glycolytic enzymes can provide more insight into how glycolysis promotes the development of pulmonary fibrosis and expand therapeutic options." (PMID 38203486, 2023). "Activated HIF-1α participates in murine bleomycin-induced pulmonary fibrosis and human idiopathic pulmonary fibrosis." (PMID 38012636, 2023). "The hypoxia-inducible factor-1α/endoplasmic reticulum stress signaling pathway (HIF-1α/ERS) has a crucial role in the pathogenetic mechanism of pulmonary fibrosis (PF)." (PMID 37762310, 2023). "In fact, it has been shown that HIF-1α can regulate paraquat poisoning-induced early pulmonary fibrosis by regulating EMT via the Snail and β-catenin pathways." (PMID 36589681, 2022). "Our results confirmed that HIF-1α improved the expression of marker of pulmonary fibrosis in bleomycin-induced condition in vitro." (PMID 34868320, 2021). "All experiments showed that the inhibitory effect of Rg3 on bleomycin-induced pulmonary fibrosis was achieved by preventing the nuclear localisation of HIF-1α, thus inhibiting the TGFΒ1-mediated EMT process." (PMID 33639908, 2021). "In pulmonary fibrosis, HIF-1α, EPO, and VEGF increased with oxygen therapy, which is likely more linked to the disease’s pathogenesis and course than to hypoxemia." (PMID 34068590, 2021). "HIF-1α, a key mediator in cell metabolism and inflammation under hypoxic conditions, has recently been highlighted for functioning as a trigger of pulmonary fibrosis and also other types of fibrosis 11,17-19." (PMID 34512149, 2021). "In pulmonary fibrosis, HIF-1α, EPO, and VEGF increased with oxygen therapy, which is likely linked to the disease’s pathogenesis and clinical course rather than hypoxemia." (PMID 34068590, 2021). "Src activates HIF-1α, and as such, KX-01 can disrupt HIF-1α accumulation and thereby alleviate pulmonary fibrosis." (PMID 34349652, 2021). "HE and Masson staining revealed that the expression of HIF-1α accelerated the lung fibrosis inhibited by Rg3." (PMID 33639908, 2021). "We conclude that different levels of HIF-1α and NF-κB expression at different stages of pulmonary fibrosis in rats is positively correlated with the disease severity." (PMID 33495418, 2021). "Evidence indicates that IPF lungs show transcriptional activation of hypoxia (mainly HIF-1α), and the knockout mice for HIF-1α showed reduced lung fibrosis." (PMID 34361103, 2021). "After ginsenoside Rg3 treatment, the nuclear localization of HIF-1α decreases, thereby slowing down the process of pulmonary fibrosis." (PMID 33639908, 2021). "We studied the expression of HIF-1α and NF-κB during different stages of pulmonary fibrosis and the intervention effect of resveratrol on pulmonary fibrosis in rats." (PMID 33495418, 2021).
pulmonary fibrosis (continued). "We found elevated expression of HIF-1α in the lung tissues of rats following BLM-induced pulmonary fibrosis, mainly localized to around small blood vessels, inner macrophages, and a few inflammatory cells in the lung interstitium." (PMID 33495418, 2021). "The aim at the present study was to confirm that HUCMSCs have preventive or therapeutic effects on bleomycin-induced pulmonary fibrosis in vivo and in vitro, and HIF-1α played a key role in this process." (PMID 34868320, 2021). "Our enrichment analyses showed that after such oxidative stresses, some signaling pathways such as the HIF1-α signaling pathway are activated that can lead to ferroptosis or cell apoptosis through inducing free radicals’ generation after pulmonary fibrosis." (PMID 35069688, 2021). "Data from pulmonary fibrosis mouse models and IPF patients have revealed increased HIF1α expression in alveolar epithelial cells at an early stage of pulmonary fibrosis." (PMID 33805152, 2021). "No further reductions in proliferation or protein expression were observed in cells treated with both KX-01 and ROT, thus suggesting that KX-01 ameliorates experimental pulmonary fibrosis at least in part by inhibiting the activity of HIF-1α." (PMID 34349652, 2021). "For example, EndMT occurs in the early stage of radiation-induced pulmonary fibrosis and is dependent on Hif1a expression." (PMID 33771973, 2021). "Based on the results of our study, we conclude that resveratrol reduces the inflammatory response and lung damage in pulmonary fibrosis by inhibiting the expression of HIF-1α and NF-κB." (PMID 33495418, 2021). "For example, HIF-1α inhibition via the treatment of 17-DMAG results in reduced pulmonary fibrosis and A2BAR expression in the late stages of murine bleomycin-induced lung fibrosis in vivo." (PMID 33519814, 2020). "2ME inhibits hypoxia- and irradiation-induced EndoMT and lung fibrosis via downregulation of HIF1α-dependent Smad signaling." (PMID 31877978, 2019). "Hypoxia-induced Endo-MT in a model of radiation-induced pulmonary fibrosis was mediated through HIF-1α." (PMID 31772711, 2019). "HIF-1α represents a central regulator of glycolysis energy metabolism involved in organ fibrosis and a key player in the pathogenesis of lung fibrosis." (PMID 29186898, 2017). "For example, the PI3K-Akt pathway contributes to pulmonary fibrosis by inducing expression of HIF-1α and VEGF." (PMID 29045477, 2017). "These in vitro results further suggested that EMT acts as a mechanism in PQ poisoning‐induced early pulmonary fibrosis and that HIF‐1α is an important modulator of this process." (PMID 26781174, 2016). "We found that HIF‐1α expression increases and that alveolar epithelial cells acquire a mesenchymal cell phenotype in PQ poisoning‐induced early pulmonary fibrosis." (PMID 26781174, 2016). "Further, data from pulmonary fibrosis mouse models and idiopathic pulmonary fibrosis patients have revealed increased HIF-1α expression in alveolar epithelial cells at an early stage of pulmonary fibrosis." (PMID 27345301, 2016). "Pulmonary fibrosis often leads to severe hypoxia in lung tissues, and previous studies have observed the elevation of HIF-1α expression in lung fibroblasts exposed to bleomycin." (PMID 26819949, 2015). "Our study group seminally reported an early overexpression of HIF-1a during disease course both in the experimental model of pulmonary fibrosis and in actual human disease." (PMID 23181555, 2012). "Among them, the role of HIF-1a signaling was further investigated and revealed overexpression of HIF-1a in the alveolar epithelium, both in the bleomycin-model and human pulmonary fibrosis suggesting a role in disease initiation and progression." (PMID 19250543, 2009).